ARG1 (arginase 1)
Diseases named in the same sentence as ARG1 in open-access papers (continued):
Sharing a sentence is not in itself a finding about the gene and the disease.
hemolytic-uremic syndrome (1 paper, 2024). Acute kidney injury associated with microangiopathic hemolytic anemia and thrombocytopenia. "Hemolysis is a cardinal feature of hemolytic uremic syndrome (HUS) and during hemolysis excess arginase 1 is released from red blood cells." (PMID 38178089, 2024).
hemorrhagic stroke (1 paper, 2023). A stroke caused by a bleed on the brain. "In hemorrhagic stroke, rhCDNF treatment did not increase the density of ARG1-positive cells, but rather modestly decreased the density of CD68-positive cells in the lateral peri-hematoma striatum." (PMID 36792604, 2023).
hepatoid carcinomas (1 paper, 2021). "However, adenocarcinomas in various organs may show positivity for Arg-1, although the frequency is low, and hepatoid carcinomas occasionally exhibit positive staining for Arg-1." (PMID 34071338, 2021).
hippocampal atrophy (1 paper, 2021). "Remarkably, Arg1 overexpression mitigated hippocampal atrophy in transgenic mice, but Arg1 deletion in myeloid cells increased tau accumulation relative to Arg1-sufficient mice." (PMID 33811757, 2021).
hookworm infection (1 paper, 2017). "Our results demonstrate that hookworm infection induces a significant difference in iNOS but not in Arg-1 gene expression between individuals from the HWI and NI groups, which supports the hypothesis of regulatory rather than an alternative profile of activation." (PMID 28390393, 2017).
hyperthyroidism (1 paper, 2022). Overactivity of the thyroid gland resulting in overproduction of thyroid hormone and increased metabolic rate. "For hyperthyroidism, the candidate gene ARG1 encodes Arginase 1, a cytosolic enzyme that participates in the urea cycle and is expressed in the liver." (PMID 35782544, 2022).
Ileitis (1 paper, 2024). "Ileitis in SHIP-1−/− mice is characterised by arginase-1-dependent fibrosis." (PMID 39432107, 2024).
imbalance (1 paper, 2023). "For patients with autoimmune imbalance after trauma, ARG1 has research value." (PMID 36918848, 2023).
immune deficiency (1 paper, 2025). "In the process of GSEA results of the four diagnostic genes (APRT, ARG1, UMPS, and LDHB) suggested that these four diagnostic genes were mainly enriched in mitochondrial gene expression, primary immune deficiency, other energy metabolism-related functions, and immune-related pathways." (PMID 40774030, 2025).
immunosuppression (1 paper, 2018). "Previous studies have demonstrated that ARG1 is significantly involved in anti-inflammation, immune response, tumor immunity, and immunosuppression-related diseases for its metabolic enzyme activity in immune cells." (PMID 30320132, 2018). "Recent studies confirm that ARG1 is induced in alternatively activated (M2) macrophages and participates in anti-inflammation, tumor immunity, tumor proliferation, metastasis, and immunosuppression-related diseases." (PMID 30320132, 2018). "The past research works shed light on the fact that ARG1 participates in anti-inflammation, tumor immunity, and immunosuppression-related diseases." (PMID 30320132, 2018).
interstitial lung disease (1 paper, 2023). A diverse group of lung diseases that affect the lung parenchyma. "The ENST00000604692 expression level was significantly higher in the ILD than the without interstitial lung disease (NILD) group; T311354 and arginase-1 were significantly higher in SSc than RA group." (PMID 38125642, 2023).
joint disease (1 paper, 2022). "For this purpose, we treated mice that received MCTR3-reprogrammed monocytes with the Arg-1 inhibitor Nω-hydroxy-nor-ʟ-arginine (nor-NOHA) and assessed joint disease activity." (PMID 35430453, 2022).
Kawasaki disease (1 paper, 2024). A rare inflammatory disease characterized by an acute febrile, systemic, self-limiting, medium-vessel vasculitis primarily affecting children. "Plasma concentrations of ARG1, CCL20, CD163, CORIN, CXCL9, PCSK9 and ADAMTS2 were quantified in MIS-C (n = 22), Kawasaki disease (n = 23), definite bacterial (n = 28) and viral (n = 27) disease and healthy controls (n = 8)." (PMID 38359342, 2024).
leprosy (1 paper, 2022). Leprosy is a chronic infectious disease affecting primarily the skin and peripheral nervous system. "In contrast, arginase 1 activities were higher in contacts when compared with both healthy donors and leprosy patients." (PMID 35552484, 2022). "A cross-sectional analysis was performed to compare both ARG1 and HO-1 expression in samples collected from contacts that developed leprosy (DD) in comparison with contacts that did not develop the disease (NDD)." (PMID 35552484, 2022).
Listeria infection (1 paper, 2019). "The western blotting results verified this polarization tendency; CCR7 expression was significantly higher after Listeria infection than in the control group, while the results of the expression of the M2 marker Arg-1 was opposite." (PMID 31133815, 2019).
liver abscesses (1 paper, 2018). "Expression of iNOS and Arg-1 genes was analyzed by qRT-PCR to examine differences in macrophage polarization in liver abscesses induced by the two species of Entamoeba trophozoites." (PMID 29420539, 2018).
liver cirrhosis (1 paper, 2022). "However, GPC3 could be more specific for HCC than ARG1, which will be important for differentiating HCC from liver cirrhosis." (PMID 35331259, 2022).
liver failure (1 paper, 2021). A liver disease characterized by the liver losing or has lost all of its function. "Some patients with ARG1 deficiency who develop neonatal cholestasis require LT owing to liver failure." (PMID 34646736, 2021).
lung neoplasm (1 paper, 2011). A benign or malignant, primary or metastatic neoplasm involving the lungs. "Overall from previous and current tumor analyses using different dosing regimens, carcinogens, and strains of mice, a panel of common transcripts (e.g. Arg1, Areg, Ereg, Ccr2, Cdkn1a, Gja1, Ptgis, Spp1) may provide a useful tool for early diagnosis of lung neoplasm." (PMID 22039513, 2011).
MALT lymphoma (1 paper, 2019). An indolent, extranodal type of non-Hodgkin lymphoma composed of small B-lymphocytes (centrocyte-like cells). "In the present study as well, MDSCs accumulated in large numbers in MALT lymphoma tissues and expressed high levels of Arg-1 and iNOS, suggesting an important role in the development of MALT lymphoma." (PMID 32063899, 2019). "Since Arg-1/iNOS overexpression is a key mechanism through which MDSCs mediate local immune suppression, it is likely involved in creating an immunosuppressive MALT lymphoma microenvironment as well." (PMID 32063899, 2019). "In addition, the expression of arginase-1 and inducible nitric oxide synthase was significantly elevated both in gastric MALT lymphoma tissues and H. felis-infected stomach." (PMID 32063899, 2019). "Furthermore, the CD33+CD11b+ MDSCs were also enriched in the gastric MALT lymphoma biopsies, which correlated with significant upregulation of Arg-1 and iNOS compared to paired normal gastric tissues." (PMID 32063899, 2019). "Furthermore, Arg-1 was significantly upregulated in the stomach of H. felis-infected mice, indicating MDSCs activation in response to gastric MALT lymphoma development, whereas iNOS levels were not altered." (PMID 32063899, 2019).
megakaryoblastic leukemia (1 paper, 2021). "The dominant component of this model correlated with αSMA−PDGFRα+ fibroblast‐like cell content (p = 2.4E‐05) and Arg1+ macrophage content (p = 2.2E‐04) and was driven by serum response factor (SRF), possibly in a megakaryoblastic leukemia‐1/2 (MKL1/2) dependent manner." (PMID 34185408, 2021).
membranous nephropathy (1 paper, 2023). "In patients with primary membranous nephropathy, increased expression of IL‐6 secreted by MDSCs expands MDSCs and increases Arg‐1 production for Th17 cell differentiation and IL‐17A production." (PMID 37382257, 2023).
meningioma (1 paper, 2025). A generally slow growing tumor attached to the dura mater. "Standard immunohistochemistry, with the antibodies Iba1 as a pan-marker for “all TAMs”, iNOS for M1 and Arginase 1 for M2 TAMs, was performed to investigate their infiltration in the meningioma tissue." (PMID 40359417, 2025).
mesothelioma (1 paper, 2023). A usually malignant and aggressive neoplasm of the mesothelium which is often associated with exposure to asbestos. "We found that the structural changes in M2 included ARG1, CD206, CD163, FN1, and MRP8, confirming the potential value of these markers to identify M2-like TAMs in patients with mesothelioma." (PMID 37958292, 2023).
metastatic colorectal cancer (1 paper, 2025). "In this context, we investigated the prognostic and predictive significance of the NOS2/ARG1 axis and immune cell ratios in chemotherapy combined with cetuximab in wt-KRAS metastatic colorectal cancer." (PMID 41573553, 2025).
myeloproliferative neoplasm (1 paper, 2023). A clonal hematopoietic stem cell disorder, characterized by proliferation in the bone marrow of one or more of the myeloid (i.e., granulocytic, erythroid, megakaryocytic, and mast cell) lineages. "Arginase-1 (ARG1) and Programed death ligand-1 (PD-L1) play a vital role in immunosuppression in myeloproliferative neoplasms (MPNs) and directly inhibit T-cell activation and proliferation." (PMID 36911725, 2023).
neuroma (1 paper, 2022). A tumor that grows from a nerve or is composed of nerve cells and nerve fibers. "Compared with neuroma cell cultured alone, secretions of M1 macrophage-inducible factors, such as IFN-γ and TGF-ß, were increased after adding the HuD protein, while the secretions of M2 macrophage-inducible factors, such as IL-4 and Arg-1, were decreased." (PMID 35294333, 2022).
neuropathic pain (1 paper, 2025). Chronic pain caused by damage to nerve fibers. "EE can relieve neuropathic pain by reducing inflammatory mediators, such as proinflammatory cytokines (IL-1β, TNF-α, IL-6) and chemokines (CCL2, CCL3), among others, increasing anti-inflammatory substances (IL-10, Arg-1, CX3CL1) in the periphery and CNS." (PMID 40190342, 2025).
neutropenia (1 paper, 2023). A decrease in the number of neutrophils found in the blood. "Further reduction in ARG1 in AA and PGF patients is likely the result of ongoing neutropenia and may also contribute to the dysregulated T-cell activation in these conditions." (PMID 37818364, 2023).
Nocardia infection (1 paper, 2022). "Therefore, we detected the expression of markers of M1 (iNOS, CXCL-10, and CD86) and M2 (CD206 and ARG1) microglia after Nocardia infection using BV2 cells." (PMID 36352407, 2022).
oral cancers (1 paper, 2021). "In stark contrast, decreased RXFP3 expression suggests that oral cancer cells fail to perambulate increased DNA damage, a phenomenon that is associated with heightened metabolism and ROS production and occurs in response to ARG1 overexpression." (PMID 34885177, 2021). "The effect of ARG1 overexpression on the migratory ability of oral cancer cells in vitro was determined by a wound-healing assay." (PMID 34885177, 2021). "Further, it is unclear how tolerable, yet effective doses of an ARG1 inhibitor will be achieved in oral cancers because they have already tweaked arginine metabolism to their advantage via reduced ARG1." (PMID 34885177, 2021). "Taken together, these data indicate that ARG1 overexpression inhibits the migration and the invasion of oral cancer cells in vitro." (PMID 34885177, 2021). "Various functional studies show that ARG1 overexpression in oral cancer cells inhibits cell proliferation and invasion compared with controls." (PMID 34885177, 2021). "The results showed that ARG1 overexpression had an inhibitory effect on proliferation and viability of oral cancer cells in a time-dependent manner as the cell numbers decreased over time." (PMID 34885177, 2021). "While these are up- or downstream events, these data suggest that ARG1 overexpression rewires oral cancer cell signaling to prime a dampened natural killer cell associated immune response." (PMID 34885177, 2021). "Collectively, these results suggest that ARG1 overexpression inhibits the growth of oral cancer cells in vitro." (PMID 34885177, 2021). "However, we also show that a percentage of oral cancer cells survive, and a portion remains functional despite overexpression of ARG1." (PMID 34885177, 2021). "We propose that manipulating ARG1 may not be therapeutically viable for oral cancers due to their unique and complex biology presented here." (PMID 34885177, 2021). "However, considering that ARG1 overexpression led to downregulation of RXFP3, it is tempting to speculate that this signaling axis may dampen oral cancer cellular ability to cope with DNA damage stress." (PMID 34885177, 2021).
oral candidiasis (1 paper, 2023). Infection of the mucosal lining of the mouth with the fungus Candida albicans. "Expansion of PMN-MDSCs in response to oral candidiasis was confirmed by the immunosuppressive activity on CD4 + T cells by Ly6G + Arg1 + cells." (PMID 37886517, 2023).
pancreatitis (1 paper, 2017). Inflammation of the pancreas. "(E) qRT-PCR for Arg1 and Chil3 expression in myeloid cells flow-sorted from control spleen, iKras* pancreata 3 weeks post pancreatitis and 3 days post Kras* inactivation." (PMID 28980940, 2017).
papillary lung adenocarcinoma (1 paper, 2016). A morphologic variant of lung adenocarcinoma characterized by the presence of papillary structures. "An important finding of the present study was the strong > 14-fold induction of arginase-1 in large papillary lung adenocarcinomas to suggest arginine dependent tumor growth." (PMID 27602772, 2016).
papilloma (1 paper, 2020). A benign epithelial neoplasm that projects above the surrounding epithelial surface and consists of villous or arborescent outgrowths of fibrovascular stroma. "Elevated NO and arginase activity in the mSCC38 model was consistent with our finding that transcription of Nos2 and Arg1 was increased in neutrophils from tumors and papillomas of DMBA/PMA-treated mice, compared to surrounding skin." (PMID 32664318, 2020).
parasite (1 paper, 2013). "Thus, Arg1 activity might serve not only to control aberrant inflammation and fibrosis during parasite infection, but to also create a metabolically unfavorable environment for parasites." (PMID 24244174, 2013).
pediatric cancer (1 paper, 2015). "High expression of FOXP3, CD14, and ARG1 mRNA in the primary tumors of high-risk NB patients was predictive of better survival, suggesting that the immune status of the tumor may influence the natural history of this pediatric cancer." (PMID 26161395, 2015).
periodontal disease (1 paper, 2023). "When macrophages polarize to the anti-inflammatory M2 type, they secrete IL-10 and Arg-1 anti-inflammatory factors, and IL-10, an important immunomodulatory factor, can inhibit osteoclastogenesis and play an osteoprotective role in periodontal disease." (PMID 36686380, 2023).
pneumococcal infection (1 paper, 2022). Infections with bacteria of the species streptococcus pneumoniae. "Acute pneumococcal infection further increased the expression of IL-10 and ARG1 in the lungs of HDM-exposed mice." (PMID 35273509, 2022).
polyarthritis (1 paper, 2021). "M2 polarization was constantly deficient from the onset of polyarthritis as indicated by impaired expression of Ppar-γ, Arg-1 and Il-10." (PMID 35111160, 2021).
polycystic kidneys (1 paper, 2021). "In terms of ADPKD, comparison of gene expression profiles in kidney tissues of Pkd1-deficient versus wild-type mice identified 204 genes that were differently expressed in late-stage polycystic kidneys including Arg1." (PMID 33758231, 2021).
polyp (1 paper, 2017). A usually exophytic mass attached to the underlying tissue by a broad base or a thin stalk. "Since a decrease was also seen in colon mRNA levels of CD4 and Arg-1, it is plausible that the decreased polyp infiltrate also consisted of CD4+ T cells and type-2 macrophages." (PMID 28410235, 2017).
prostatic tumor (1 paper, 2019). "In support of these observations, increased expression of iNOS and Arg1, two genes commonly expressed by MDSCs, were also observed in prostatic tumor tissues of the Cdh1L/L:PtenL/L:PB-Cre4 compound mice in comparison with either PtenL/L:PB-Cre4 or Cdh1L/L:PB-Cre4 mice." (PMID 31658259, 2019).
pulmonary embolism (1 paper, 2024). The obstruction of the pulmonary artery or one of its branches by an embolus, sometimes associated with infarction of the lung. "One patient died of pulmonary embolism, which may have been indirectly related to arginase 1 deficiency." (PMID 39512428, 2024).
pulmonary TB (1 paper, 2020). "iNOS and arginase-1, a surface marker of polarized macrophages, were quantified by immunohistochemical staining and imaging analysis of lung tissues of patients who underwent surgical treatment for pulmonary TB." (PMID 31996142, 2020).
rectal cancer (1 paper, 2023). A primary or metastatic malignant neoplasm that affects the rectum. "We employed 10 pairs of clinical specimens of colon and rectal cancer to detect the expressions of the M2 macrophage marker Arg1 and the inflammatory transformation marker NF-κB p65 via immunohistochemistry." (PMID 37537587, 2023).
renal tumors (1 paper, 2025). "Another limitation of this report is the unavailability of arginase-1 staining for the pulmonary and renal tumors due to limited residual biopsy material." (PMID 41464171, 2025).
respiratory failure (1 paper, 2021). The significant impairment of gas exchange within the lungs resulting in hypoxia, hypercarbia, or both, to the extent that organ tissue perfusion is severely compromised. "Respiratory failure was signified by depression of EGF, GZMA, LAP, IL-4, and IL-7, and increased expression of MUC-16, ARG-1, and LAMP-3." (PMID 34177897, 2021).
retinal (1 paper, 2023). "First, endogenous arginase 1 (A1) but not A2 limits the induction of IL-1β in retinal macrophages after IR injury in vivo as a possible mechanism of protection; this finding complements our earlier observation that A1 also limits expression of TNF-α in retinal IR injury." (PMID 37735154, 2023).
retinopathy of prematurity (1 paper, 2023). A bilateral retinopathy characterized by neovascularization, scarring, retinal detachment, and eventually blindness. "We have previously shown that the cytosolic isoform, Arginase 1, has a neuroprotective role in models of ischemia-reperfusion (IR) injury and retinopathy of prematurity (ROP)." (PMID 37816735, 2023).
salmonellosis (1 paper, 2021). Infections with bacteria of the genus salmonella. "Our results in murine systemic salmonellosis necessitate a comparison with previous data on the role of ARG1 during infections with other intramacrophage pathogens such as the protozoan parasite Leishmania (L.)major." (PMID 34359992, 2021). "Based on our results, we conclude that targeting of ARG1 is not a treatment option in patients with systemic salmonellosis, including typhoid fever." (PMID 34359992, 2021).
SARS-CoV infection (1 paper, 2025). "This is not surprising, as in SARS-CoV infection, Arg1+ AAM was shown to be important in regulating immune-mediated pathology and prevention of progression to fibrotic lung disease." (PMID 40854598, 2025).
scleroderma (1 paper, 2022). Scleroderma is a rare autoimmune connective tissue disorder characterized by abnormal hardening of the skin and, sometimes, other organs. "The result of Western blot results showed that the M1 macrophage polarization marker iNOS was upregulated and the M2 polarization macrophages marker Arg-1 was downregulated after HUMSCs-Ex interference in a mouse model of scleroderma." (PMID 34784013, 2022). "We found that HUMSCs-Ex elevated M1 macrophage markers (IL-6, IL-12p40, iNOS) and inhibited M2 macrophage markers (IL-4, IL-10, Arg-1 and CD206) in a mouse model of scleroderma, thus suggesting that HUMSCs-Ex might play an antifibrotic role by regulating the M1/M2 macrophage balance." (PMID 34784013, 2022).